CRP (C-reactive protein)
Diseases named in the same sentence as CRP in open-access papers (continued):
Sharing a sentence is not in itself a finding about the gene and the disease.
appendicitis (312 papers, 2006 to 2026). Acute inflammation of the vermiform appendix. "High CRP levels in patients with symptoms and signs of acute appendicitis are also associated with greater inflammation of the appendix." (PMID 40572758, 2025). "Right lower quadrant pain and elevated CRP levels (> 20 mg/L) were significantly associated with appendicitis (p = 0.018 and p = 0.012, respectively)." (PMID 40999376, 2025). "In our study, salivary CRP effectively distinguished appendicitis from other causes of abdominal pain, supporting its role as a useful adjunct in the diagnostic pathway." (PMID 40871545, 2025). "A logistic regression model demonstrated CRP was significantly associated with the likelihood of acute appendicitis on histopathology (OR 1.009, 95% CI 1.002-1.015, p=0.001)." (PMID 41523465, 2025). "In this study, we demonstrated that salivary CRP not only shows strong diagnostic performance for acute appendicitis but also correlates closely with serum CRP levels, a routinely used biomarker in clinical practice." (PMID 40871545, 2025). "Increased levels of all standard inflammatory markers (CRP, leukocytes, neutrophils, and neutrophil percentages) were significantly associated with increased odds of appendicitis." (PMID 40208339, 2025). "Despite its extensive application in pediatric appendicitis diagnosis, CRP has relatively mediocre diagnostic efficacy." (PMID 40804906, 2025). "ROC analysis showed CRP to be an effective diagnostic marker for prediction of acute appendicitis on histopathology, outperforming neutrophil and lymphocyte count and NLR." (PMID 41523465, 2025). "Although its diagnostic use in acute appendicitis is still under investigation, preliminary studies suggest a positive correlation between salivary and serum CRP concentrations." (PMID 40871545, 2025). "In patients with Enterobius vermicularis-associated acute appendicitis, elevated CRP, leukocytosis, and neutrophilia are common." (PMID 40400853, 2025). "Elevated NLR, NMR, PLR, NPR, and CRP were strongly associated with appendicitis, while an inverse relationship was observed with MLR." (PMID 40317523, 2025). "Among laboratory findings, elevated white blood cell (WBC) counts, neutrophilia, and increased C-reactive protein (CRP) levels were significantly associated with appendicitis." (PMID 41473919, 2025). "This study aims to develop and validate a novel scoring system that incorporates NLR, NPR, NMR, PLR, MLR, CRP levels, and temperature to improve the diagnostic accuracy of appendicitis in pediatric patients." (PMID 40317523, 2025). "Higher serum white blood cell count (WCC) and C-reactive protein (CRP) are associated with complicated appendicitis." (PMID 39735043, 2024). "We conclude that MAS in combination with CRP levels is a helpful diagnostic tool for the decision to operate in acute appendicitis, especially for junior colleagues with less experience in making clinical judgments." (PMID 39677268, 2024). "There are, however, multiple papers on the role of PTX-3, IL-6, D-dimer, and CRP in other settings of urgent acute abdomen, such as acute appendicitis, one of the main diagnostic entities to consider in the differential diagnosis of ovarian torsion." (PMID 39519217, 2024). "Serum concentration of C-reactive protein (CRP) was also found to be associated with complicated appendicitis, even after adjustment for risk factors (OR 1.012 [95% CI 1.002–1.022], p = 0.02)." (PMID 38409170, 2024). "This was echoed by a retrospective study of children with acute appendicitis, where IL-6 and other biomarkers such as CRP, immunoglobulin E (IgE), and interleukin-13 (IL-13) were found to be independent risk factors for complicated appendicitis (p < 0.05)." (PMID 38892260, 2024). "All patients suspected of having acute appendicitis should undergo laboratory testing, including total white blood cell count, percentage of neutrophils, and measurement of C-reactive protein concentration, before proceeding to further diagnostic steps." (PMID 37965237, 2023).
appendicitis (continued). "If the CRP level is below 10 mg/L and symptoms have been evident for longer than 48 h, acute appendicitis is least likely to be the cause." (PMID 37048540, 2023). "Particularly high WBC counts and high CRP values as well as indirectly a longer surgical time are indicators of severe appendicitis, which per se are likely to be associated with higher morbidity." (PMID 36708422, 2023). "Previously, studies have been conducted to affirm the association of CRP with complicated appendicitis." (PMID 35495380, 2022). "The results of this study prioritize HLX and CTSB as potential causal genes for appendicitis and suggest a shared genetic mechanism between appendicitis and CRP concentrations." (PMID 35693796, 2022). "They reported that CRP provokes PS translocation in RBCs; furthermore, treatment of healthy RBCs with different CRP concentrations, extrapolated from CRP levels present in subjects with acute appendicitis, causes PS translocation." (PMID 36498493, 2022). "Intersection and colocalization of the GWAS results were performed with appendicitis and CRP-associated loci from the Pan-UKBB cohort." (PMID 35693796, 2022). "Early changes in C-reactive protein (CRP) have been shown to have moderate diagnostic value in predicting appendicitis." (PMID 35663691, 2022). "In specialist care, CRP is of moderate diagnostic value for appendicitis, having a sensitivity of 0.62–0.85 and a specificity of 0.59–0.94 at a ≥ 10 mg/L cut-off value." (PMID 35535699, 2022). "Statistical analysis in this study showed that the onset time, preoperative temperature, leukocyte count, C-reactive protein, and operation time were independent risk factors for postoperative fever in children with acute appendicitis." (PMID 36081635, 2022). "In this study, the causal relationship between single-nucleotide polymorphisms (SNPs) associated with circulating CRP concentrations and the risk and severity of acute appendicitis was investigated." (PMID 35693796, 2022). "We aimed to determine the diagnostic characteristics of CRP testing for appendicitis in primary care and to assess the value of adding CRP to basic clinical assessment." (PMID 35535699, 2022). "A genome-wide association study (GWAS) on CRP concentrations and appendicitis severity was performed." (PMID 35693796, 2022). "The first study found to report an association between increased levels of C-reactive protein and acute appendicitis was carried out by Mikaelsson C and Arnbjornsson E in 1984." (PMID 35106154, 2022). "The complicated appendicitis was significantly associated with increased age, pain duration, neutrophilia, high C-reactive protein, fecalith presence, and free fluid." (PMID 35692621, 2022). "High serum CRP level was significantly associated with complicated appendicitis (p < 0.001), and the predicted existence rates of complicated appendicitis were 52.7% for serum CRP level ≥50mg/L, 74.4% for ≥100mg/L, and 82.6% for ≥150mg/L." (PMID 34314464, 2021). "We aimed to determine the (added) diagnostic value of CRP for appendicitis in children with acute abdominal pain in primary care." (PMID 33789755, 2021). "For example, Qi and Zhang reported that the neutrophil percentage and CRP were risk factors for gangrenous appendicitis based on logistic regression analysis." (PMID 34011068, 2021). "The results of univariate analysis demonstrated that age, body temperature, RLQ pain duration, NLR, and CRP were significantly associated with complicated appendicitis." (PMID 34645500, 2021). "Studies on the diagnostic value of WBC and CRP for diagnosing appendicitis in children have reported contradictory results." (PMID 32953890, 2020). "Our study suggested that elevated levels of neutrophil percentage (>74%) and CRP (>8 mg/dL) predicted that the risk of perforated appendicitis is increased more than 5 times." (PMID 31641539, 2019).
appendicitis (continued). "C-reactive protein (CRP) is an acute phase protein that is often relied-on by many surgeons as a diagnostic marker of acute appendicitis." (PMID 29793425, 2018). "Based on our findings, we conclude that CRP levels at admission and its early change 3 h later, in patients with clinically suspected acute appendicitis, has a moderate diagnostic value." (PMID 29793425, 2018). "The diagnostic performance of both CRP and delta CRP in predicting acute appendicitis were further analyzed by using the ROC curves." (PMID 29793425, 2018). "Early change of CRP has a moderate diagnostic value in patients with clinically suspected acute appendicitis." (PMID 29793425, 2018). "As far as we know, this is the largest study to prospectively evaluate the diagnostic value of early variation of CRP concentrations in subjects presenting to the ED with clinically suspected appendicitis." (PMID 29793425, 2018). "Elevated international normalized ratio (INR) and serum C-reactive protein (CRP) were associated with complicated appendicitis (p = 0.001)." (PMID 27330547, 2016). "It was determined that 1-unit increase in disulphide/native thiol rate predicts 1.368 times the risk of having perforated appendicitis and 1-unit increase in CRP level predicts 1.635 times the risk of having perforated appendicitis." (PMID 27642237, 2016). "In conclusion, elevated INR and CRP were associated with complicated appendicitis and longer hospital stay." (PMID 27330547, 2016). "With regard to laboratory study, an increase in white blood cell count (WBC), predominance of polymorphonuclear leukocytes (PMN), and increased C-reactive protein (CRP) levels were associated with the risk and severity of complications in appendicitis." (PMID 26380377, 2015). "The aim of our study was to determine the diagnostic accuracy of TLC, CRP and neutrophil count in combination in the diagnosis of acute appendicitis." (PMID 19568576, 2009). "Elevated NLR and CRP have been consistently associated with increased likelihood of appendicitis and may also predict complicated cases." (PMID 40317523, 2025). "CRP is an important diagnostic biomarker in acute appendicitis." (PMID 40871545, 2025). "Moreover, elevated inflammatory markers, such as CRP, were significantly associated with appendicitis, reaffirming their role in guiding clinical decisions." (PMID 40999376, 2025). "In addition, high CRP levels were also associated with the histopathological status of the appendix, with the highest levels seen in gangrenous appendicitis." (PMID 40572758, 2025). "Our results indicate that urine LRG1 might have the potential to differentiate between uncomplicated and complicated appendicitis in children, but with a lesser accuracy than currently more readily available diagnostic aids such as CRP and AIR score." (PMID 40208339, 2025). "Furthermore, studies suggest that elevated NLR or CRP levels are associated with the development of complicated appendicitis and intra-abdominal abscesses." (PMID 39735250, 2024). "C-reactive protein (CRP) is an acute phase reactant strongly associated with infection; significant rises can be strongly associated with significant intraabdominal bacterial infections such as those causing appendicitis." (PMID 39677268, 2024). "CRP levels above 34.13 mg/L were associated with longer LOS in pediatric appendicitis patients." (PMID 39726534, 2024). "Interestingly, meta-analysis of the diagnostic value of inflammatory markers for suspected acute appendicitis revealed that CRP is the most important inflammatory marker, followed by leucocyte count and procalcitonin." (PMID 39451658, 2024). "To date, several biomarkers, such as fibrinogen, red cell distribution width, mean platelet volume, interleukins, CRP, procalcitonin, 5-hydroxyindoleacetic acid, hyponatremia or hyperbilirubinemia, have been investigated for acute appendicitis with varying diagnostic accuracy in published studies." (PMID 37048540, 2023).
appendicitis (continued). "When CRP was ≥ 34.82 mg/L, we observed 6.24 times increase in the risk of complicated appendicitis." (PMID 37393302, 2023). "To test whether CRP concentrations are genetically related to acute appendicitis, we looked for enrichment of CRP-associated SNPs in appendicitis GWAS." (PMID 35693796, 2022). "Regardless of being retrospective, the study by Yang at al. had the largest sample size (1895 children) and demonstrated that elevated levels of neutrophil percentage (>74%) and CRP (>8 mg/dL) combined, increased the risk of complicated appendicitis more than five times." (PMID 35884054, 2022). "Therefore, in this study, the causal relationship between SNPs associated with circulating CRP concentrations and the risk and severity of acute appendicitis was investigated." (PMID 35693796, 2022). "CRP >84 mg/L was significantly associated with gangrenous appendicitis in the same study." (PMID 35495380, 2022). "Complicated appendicitis (CA) has a delayed presentation with predictable risk factors comprising age > 50 years, female sex, symptoms of 2 days, elevated Alvarado score, C-reactive protein (CRP) > 100 mg/L, and high infection rate postoperatively in diabetic patients." (PMID 35692621, 2022). "Significant enrichment of CRP-QTLs in association with appendicitis was observed." (PMID 35693796, 2022). "Our analysis found serum level of CRP, defined as ≥ 50 mg/L, was significantly associated with complicated appendicitis (p < 0.001), and three clinical scoring models that showed significance for predicting complicated appendicitis used level of CRP for their scoring." (PMID 34314464, 2021). "Research on the risk factors for developing complicated appendicitis is still lacking, although age, female gender, obesity, diabetes mellitus, immunocompromised states, duration of symptoms, a higher Alvarado score and high CRP have been shown to be associated with complicated appendicitis." (PMID 35115895, 2021). "Additionally, The Royal College of Surgeons of England published a prospective study involving the use of WBC and CRP in the diagnostic accuracy of acute appendicitis." (PMID 31856705, 2019). "For complicated appendicitis, CRP has the highest degree of diagnostic accuracy." (PMID 27274988, 2016). "CRP monitoring enhances the diagnostic accuracy of acute appendicitis." (PMID 22866907, 2012). "This study investigated whether CRP is a surgical indication marker as well as a diagnostic marker for the decision of an emergency operation for acute appendicitis." (PMID 19878592, 2009). "Additionally, C-reactive protein (CRP) has been identified as a trigger for eryptosis, with a strong association between CRP levels and eryptosis rate in acute inflammatory conditions, such as peritonitis and acute appendicitis." (PMID 40643488, 2025). "In addition, CRP was classified as a trigger for eryptosis, and a strong association between CRP and eryptosis was confirmed in acute inflammatory conditions, such as peritonitis and acute appendicitis." (PMID 40592821, 2025). "Nevertheless, our study shows that the combination of MAS/CRP yields significantly better sensitivity and specificity as compared to clinical judgment and provides further evidence for the argument of using diagnostic factors in combination when deciding on a diagnosis of acute appendicitis." (PMID 39677268, 2024). "Therefore, CRP had the highest diagnostic accuracy in complicated appendicitis (AUC: 0.887)." (PMID 27274988, 2016). "Inferential analysis confirms that delayed consultation and elevated CRP are predictors of complicated appendicitis in pregnancy." (PMID 41658481, 2026). "A cutoff of 4.3 mg/dL yielded 74% sensitivity and 77% specificity, while CRP ≥ 10 mg/L demonstrated 87% sensitivity and 77% specificity for appendicitis overall." (PMID 41517643, 2026). "In multivariable analysis, log-transformed CRP and SII remained independently associated with complicated appendicitis (both p < 0.001)." (PMID 42073025, 2026).
appendicitis (continued). "This is in accordance with previous data, which report CRP to be a sensitive and reliable factor for appendicular perforation, particularly at levels > 40 mg/L when combined with clinical scores such as appendicitis inflammatory response (AIR) score or PAS." (PMID 41517643, 2026). "In some studies, all children with perforations had a CRP > 20 mg/L (median 96 mg/L, compared to 5 mg/L in non-appendicitis cases)." (PMID 41517643, 2026). "In afebrile patients with low inflammatory markers (CRP < 100), 8.9% of respondents would operate overnight based on clinical suspicion of acute appendicitis, rising to 21.1% if the diagnosis had been confirmed with pre-operative imaging." (PMID 41507411, 2026). "All these findings correlate with the results of this study, as leukocytes and CRP were significantly increased compared to the control group with simple and complicated appendicitis." (PMID 41470162, 2025). "Salivary CRP levels were significantly elevated in children with acute appendicitis than in controls, closely mirroring serum CRP trends." (PMID 40871545, 2025). "The median CRP level in saliva was significantly higher in the appendicitis group (35.7 mg/L) compared to controls (1.1 mg/L), with p < 0.001." (PMID 41153524, 2025). "CRP levels were significantly higher in CAA than uncomplicated acute appendicitis (UAA; Median 48.4 vs. 8.8 mg/L; p < 0.001) and increased progressively with disease severity." (PMID 40825891, 2025). "This study aims to evaluate a modified APPEND score (mAPPEND), excluding CRP for diagnosing appendicitis in a New Zealand Pasifika cohort." (PMID 39969408, 2025). "In blood tests, WBC counts and CRP levels are known to be useful for diagnosing acute appendicitis, and a complete blood count is widely used for evaluating patients with abdominal pain." (PMID 41362537, 2025). "Given its strong association with complicated appendicitis, even modest reductions in serum sodium could serve as an early warning sign prompting more urgent surgical evaluation or imaging, particularly when combined with elevated levels of CRP and neutrophilia." (PMID 40506956, 2025). "White blood cell (WBC) count and C-reactive protein (CRP) are the two most commonly utilized labs in the diagnosis of acute appendicitis." (PMID 40400853, 2025). "A CRP cut-off of ≥3.95 demonstrated a sensitivity of 75.60% and specificity of 61.48% for prediction of acute appendicitis on histopathology (AUC 0.712, p<0.001)." (PMID 41523465, 2025). "The mean CRP level for patients with visualized appendicitis was 41 mg/L (normal value <5), while those who underwent appendicectomy had a mean CRP level of 31 mg/L." (PMID 40718251, 2025). "The results of our study, largely supported by the available literature, suggest CRP is an effective adjunct to assess the need for operative intervention in paediatric patients with clinical concern for appendicitis." (PMID 41523465, 2025). "All cases of acute gastro-intestinal pathology in our series occurred in the CRP high cohort, mirroring surgical data that link elevated CRP with appendicitis and diverticulitis." (PMID 41204018, 2025). "This work shows the individual diagnostic power of serum C-reactive protein concentration, fibrinogen, and INR in detecting the severity of appendicitis." (PMID 39996695, 2025). "Among these, a mean CRP of 45 mg/L for patients who underwent appendicectomy and a mean CRP of 41 mg/L for patients with positive appendicitis pathology were observed." (PMID 40718251, 2025). "CRP is the most effective biomarker for diagnosing acute perforated appendicitis, with the highest sensitivity, specificity, and NPV." (PMID 40067493, 2025). "A recent study that similarly noted significantly higher CRP levels in all cases of Campylobacter gastroenteritis compared to patients with appendicitis." (PMID 40901534, 2025). "The levels of CD8 lymphocytes and CRP were significantly higher in patients with complicated appendicitis." (PMID 41470162, 2025).